MSLN (mesothelin)
Diseases named in the same sentence as MSLN in open-access papers (continued):
Sharing a sentence is not in itself a finding about the gene and the disease.
mesothelioma (continued). "In accordance with these findings, CD26hi/CD4+ T cells genetically engineered to express a CAR recognizing mesothelin, an antigen overexpressed in mesothelioma, displayed an outstanding capacity to traffic to, survive in, and regress solid tumors in NSG xenograft mesothelioma models." (PMID 34885056, 2021). "In a mesothelioma mouse model treatment with anti-mesothelin CAR-T cells did not lead to objective responses." (PMID 32325898, 2020). "Indeed, MSLN was shown to stimulate the expressions of ALDH, SNAIL, SLUG and TWIST, while decreasing expression of E-cadherin in lung carcinoma and mesothelioma cell lines." (PMID 32517181, 2020). "Mesothelin is a glycophosphatidylinositol (GPI)-anchored protein, identified as an antigen in several human cancers affecting the pancreas, endometrium, ovary, and lung, as well as in mesothelioma and pediatric leukemia." (PMID 32942548, 2020). "ERC/mesothelin is expressed in most cases of the epithelioid type, but not in the sarcomatoid type of mesothelioma." (PMID 32677949, 2020). "This was in line with the results of another independent study that confirmed MSLN reactivity in all 44 epithelioid mesotheliomas and in the epithelial components of 3 biphasic mesotheliomas, but not in any of 8 sarcomatous mesotheliomas examined." (PMID 31463062, 2019). "We also examined the sensitivity, specificity, positive and negative predictive values of mesothelin, midkine, and the combination of the biomarkers to differentiate patients of mesothelioma from other patients." (PMID 28335760, 2017). "In contrast, a panel with 13 kinds of marker proteins which did not include mesothelin detected stage I and II mesothelioma with a sensitivity of 88% under 92% accuracy." (PMID 28335760, 2017). "Baseline serum mesothelin and midkine levels at the diagnosis were not related to the chemotherapy responses of mesothelioma patients." (PMID 28335760, 2017). "These markers, including megakaryocyte potentiating factor, fibulin-3, osteopontin, CA125 and hyaluronic acid, were not as accurate as mesothelin to differentiate mesothelioma from various non-mesothelioma diseases." (PMID 28335760, 2017). "The results indicated that mesothelin showed a sensitivity of 32% at 95% specificity and furthermore about 70% of mesothelioma patients at the early stage were judged as negative for mesothelin." (PMID 28335760, 2017). "Our results also indicated that neither serum mesothelin or midkine discriminated mesothelioma at stage I or II from benign asbestos pleurisy." (PMID 28335760, 2017). "Mesothelin therefore differentiated mesothelioma from non-mesothelioma diseases, but midkine had a limited value only to discriminate mesothelioma from benign asbestos pleurisy." (PMID 28335760, 2017). "Serum mesothelin levels were not related to median survival of patients with mesothelioma (p = 0.541)." (PMID 28335760, 2017). "In addition to exhibiting slightly more cytotoxicity than SS1P in the NCI-H226 human mesothelioma line, YP218 Fv-PE38 also showed higher affinity than other rabbit anti-mesothelin immunotoxins on most of the cell lines." (PMID 25996440, 2015). "Serum mesothelin was elevated at baseline in all 4 mesothelioma patients and none of the pancreatic adenocarcinoma patients." (PMID 25756664, 2015). "Pathologic confirmation of mesothelin expression was not required for study entry for pancreatic adenocarcinoma and mesothelioma considering that these tumors show high mesothelin expression in nearly all cases." (PMID 25756664, 2015). "Therefore, we believe that a blood biomarker is an ideal tool for the early diagnosis of mesothelioma, and the current 7–20 ELISA system for N-ERC/mesothelin is clinically useful as an excellent biomarker for pleural mesothelioma." (PMID 25045139, 2014).
mesothelioma (continued). "Mesothelin showed a median concentration of 2.01 nmol/l (IQR 1.24–4.99 nmol/l) for epithelioid, 2.01 nmol/l (IQR 1.58–4.18 nmol/l) for biphasic, and 0.75 nmol/l (IQR 0.69–1.32 nmol/l) for sarcomatoid mesothelioma." (PMID 25469901, 2014). "Estimates of ROC analyses with 95% CI for mesothelioma after bootstrap analysis with 1,000 random samples according to maximum Youden's index (YI) and a false-positive rate (FPR) of 4% for the combination of mesothelin and miR-103a-3p." (PMID 25469901, 2014). "We found that mesothelioma cells grown as monolayers or as spheroids expressed comparable levels of mesothelin; however, spheroids were at least 100 times less affected by SS1P, an anti-mesothelin antibody-bacterial toxin chimeric protein." (PMID 22737246, 2012). "MSLN (Mesothelin) mRNA was not differentially expressed, despite its strong protein expression in mesotheliomas." (PMID 19662092, 2009). "Within mesothelioma, high MSLN expression does not necessarily portend a worse prognosis." (PMID 41400642, 2025). "The first-in-human clinical trial investigating MSLN-targeting CAR-macrophages (CAR-M) was proposed by Annunziata and colleagues, who studied peripheral blood mononuclear cell (PBMC)-derived CARs (MCY-M11), including macrophages, in patients with OC and mesothelioma (NCT03608618)." (PMID 41335396, 2025). "Given the significant overexpression of MSLN in mesothelioma, this molecule has emerged as a focal point in mesothelioma research, and its soluble derivative SMRP has been validated as an important biomarker for both diagnosis and prognostic assessment of mesothelioma." (PMID 41400642, 2025). "Indeed, being a cell surface glycoprotein expressed in different cancers, including mesothelioma, but not in the parenchyma of vital organs, mesothelin is presently regarded as an attractive therapeutic target in oncology." (PMID 40918456, 2025). "Additionally, the mesothelioma tissues exhibited significantly higher mesothelin levels (mean, 9.40; 95% CI, 7.73–11.43) than the non-cancerous organ tissues analyzed via qPCR." (PMID 39315086, 2024). "Moreover, analysis of clinical samples using qPCR demonstrated markedly elevated mesothelin expression in canine mesotheliomas compared to non-mesothelioma cases." (PMID 39315086, 2024). "Consequently, significantly higher mesothelin expression was detected in the mesotheliomas (mean, 9.40; 95% CI, 7.73–11.43) than in the non-MS tumors (mean, 0.016; 95% CI, 0.012–0.021) (p < 0.001)." (PMID 39315086, 2024). "No considerable difference in mesothelin expression was observed between benign and malignant non-mesothelioma tumors, suggesting that mesothelin overexpression is not necessary for the malignant nature of non-mesothelioma tumors." (PMID 39315086, 2024). "Our data suggest that lowered mesothelin expression level correlates with anti-cancer efficacy observed in animal studies, thus strengthening the rationale for combinatory treatment using oncolytic adenovirus AdV5/3-D24-ICOSL-CD40L with anti-PD-1 in mesothelioma therapy." (PMID 38053658, 2023). "Mesothelin was detected in all three 10 K, 18 K, and 100 K pellets derived from four of the mesothelioma cells, but not in the EVs derived from H28 cell line, although this was not surprising given the consistently low EVs and protein yield obtained from H28 cells across all experiments." (PMID 37190292, 2023). "Additionally, we describe the development of a novel ADC targeting mesothelin (MSLN), a cell surface protein that is over-expressed by a number of tumor types including mesothelioma, lung, pancreatic, ovarian, colorectal, cholangial, gastric and endometrial carcinomas." (PMID 37195923, 2023). "Furthermore, their relationship to the amount of ERC/Mesothelin in mesothelioma is not yet validated." (PMID 38854453, 2023).
mesothelioma (continued). "Mesothelin, a glycosylphosphatidylinositol (GPI)-anchored glycoprotein, is a tumor differentiation antigen frequently expressed at high levels in tumors, such as mesothelioma, ovarian, pancreatic, and lung adenocarcinomas, and showing restricted expression in nonmalignant tissues." (PMID 35008346, 2021). "Our initial hypothesis that ERC/mesothelin regulates the histological differentiation of mesothelioma was not supported by the experimental data." (PMID 32677949, 2020). "In vitro cell culture manipulations of ERC/mesothelin expression did not affect cellular morphology or proliferation, although its overexpression enhanced cellular adhesion and the migration/invasion activity of mesothelioma cells." (PMID 32677949, 2020). "Interestingly, MSLN expression levels were comparable with those found in one control mesothelioma included in the analysis (748.5 amol/μg, data not shown)." (PMID 31537838, 2019). "A positive rate of mesothelin were greater in epitheloid type than in other types, and the mesothelin expressions increased according to advanced stage diseases, whereas other studies showed that mesothelin levels were not related to the histological type or stage of mesothelioma." (PMID 28335760, 2017). "Moreover, mesothelin as part of the outer plasma membrane by GPI linkage is overexpressed in several human tumors, including mesothelioma as well as pancreatic and ovarian adenocarcinoma and was detectable in NIH:OVCAR-3 and SK-OV-3 cells in contrast to SCCOHT-1 and BIN-67 cells." (PMID 26436697, 2015). "Furthermore, we subsequently confirmed that ERC is a homolog of the human mesothelin gene, a gene that is strongly expressed in normal mesothelial cells, mesotheliomas, non-mucinous ovarian carcinomas and pancreatic ductal adenocarcinomas." (PMID 24146039, 2014). "Despite the higher fraction of mesothelioma lines positive for MSLN, it does not appear to be a completely mesothelioma specific marker as it was strongly expressed in the large cell lung carcinoma cell line T3M-10 and moderately expressed in the lung adenocarcinoma line PC-14." (PMID 21984916, 2011). "Interestingly qRTPCR across a panel of human RNAs demonstrated that MSLN is not restricted to mesothelium or mesothelioma." (PMID 21984916, 2011). "In addition, MSLN has become a popular target for targeted anti-tumor therapy due to its high differential expression, including monoclonal antibodies, antibody drug combinations (ADCs), radioimmunotherapy (RIT), CAR-T cell immunotherapy for mesothelioma, etc.." (PMID 35692779, 2022). "The AUC of serum mesothelin to distinguish patients with mesothelioma from those with metastatic cancers to pleura was significantly higher than that of serum midkine (p = 0.0330) but was not different from that of combination of both mesothelin and midkine (p = 0.0738)." (PMID 28335760, 2017). "As expected, high tumor cell MSLN expression coincided with diffuse D2-40 expression by mesothelioma cells because both proteins are located in the cellular membrane, while nuclear expression of WT-1 and BAP-1 showed non-specificity with MSLN." (PMID 37901248, 2023). "In mesothelioma, positive markers, such as CK5/6, calretinin, WT‐1, HBME‐1, thrombomodulin, mesothelin and D2‐40, are commonly used, and negative markers such as TTF‐1, CEA, MOC31, BG8 and Ber‐EP4 are rarely expressed." (PMID 35950141, 2022). "The proliferative activity of mesothelioma cells, evaluated by number of Ki-67 positive cells, was also not influenced by ERC/mesothelin expression." (PMID 32677949, 2020). "Instead, mesothelioma cells with a monophasic morphology in culture developed into biphasic cells in a mouse model, regardless of the expression of ERC/mesothelin." (PMID 32677949, 2020).
mesothelioma (continued). "Since EMT is an important process in tumor progression and metastasis, and MSLN is nonessential in most normal tissue, our findings on MSLN may provide new insights into the disease mechanisms and may aid in the development of novel targeted therapy for lung cancer and mesothelioma." (PMID 28288645, 2017). "Gastric tumors are usually smaller than mesotheliomas, and this difference in tumor mass may explain why patients with mesothelioma exhibit increased serum N-ERC/mesothelin levels, but gastric cancer patients do not." (PMID 24146039, 2014). "The lack of IHC in assessing eligibility for anti‐MSLN CAR T cell trials may be due to the presumption that MSLN‐expression is universally present and at high intensity, as reported in the earliest literature of MSLN immunostaining in mesothelioma." (PMID 37040900, 2023).
pancreatic cancer (230 papers, 2008 to 2026). "Mesothelin (MSLN), a tumor-associated antigen highly expressed in pancreatic cancer, was selected as the target in this study." (PMID 41752180, 2026). "Elevated levels of MSLN expression are identified in pancreatic cancer cells exhibiting chemoresistance, causing enhanced adhesion of cells, proliferation, migration and invasion." (PMID 40227616, 2025). "Mesothelin (MSLN), a 40‐kDa glycosylphosphatidyl inositol‐linked protein, is highly expressed in many solid tumors, including pancreatic cancer (80‐85%), while its expression is limited in normal tissues." (PMID 39887656, 2025). "We have found that MSLN can regulate EMT of tumor cells, associated with chemotherapy resistance and pancreatic cancer cells with high levels of MSLN have stronger proliferation and invasion to promote tumor development." (PMID 38628720, 2024). "Overexpression of mesothelin is associated with many different cancer cell types including pancreatic cancer." (PMID 37588093, 2023). "Mesothelin (MSLN) is a glycoprotein neo-expressed in pancreatic cancer that has been proposed as a diagnostic and therapeutic target in PaC." (PMID 36009489, 2022). "In contrast, the vaccine CRS-207 contains the live attenuated pathogen Listeria monocytogenes, which stimulate an immune response against mesothelin, a tumor-associated antigen overproduced by the pancreatic tumor." (PMID 36143975, 2022). "A variety of tumor associated antigens (TAA) expressed on pancreatic cancer cells have been targeted in various clinical trials to redirect CAR T cells against pancreatic cancer including MSLN, CEA, PSCA, MUC1, and HER2." (PMID 30809507, 2019). "We previously identified specific genes, MUC16 and mesothelin, associated with invasion and migration processes in pancreatic cancer." (PMID 30140382, 2018). "In pancreatic cancer, a previous study found that the expression of mesothelin is associated with unfavorable outcomes." (PMID 25789005, 2015). "In pancreatic cancer cells, over expression of MSLN has been implicated in significant enhancement of tumor cell growth and migration invitro." (PMID 25118887, 2014). "We aimed to assess the status of naturally occurring CD4+ and CD8+ T cell responses to a tumour associated antigen, Mesothelin, in patients with pancreatic carcinoma and study the effects of elevated IL-10 on Mesothelin-specific T cell responses." (PMID 24520352, 2014). "Increased mesothelin is associated with increased cell proliferation of pancreatic cancer cells in vitro and contributes to tumor progression in the nude mouse xenograft model." (PMID 23034174, 2012). "Mechanically, high DNA damage/DNA repair activities associated with low MSLN expression may activate the senescence pathway in pancreatic cancer cells." (PMID 40563707, 2025). "The effects of MSLN on chemoresistance and molecular mechanism underlying how MSLN promotes pancreatic cancer progression remain unclear." (PMID 38628720, 2024). "Also, the association that almost all patients with positive mesothelin were positive for CA125 expression was observed in pancreatic carcinoma." (PMID 33832498, 2021). "Furthermore, recent studies have revealed that mesothelin is associated with the invasion and migration of pancreatic cancer cells." (PMID 30140382, 2018). "In addition, fifteen of the proteins have been specifically linked to pancreatic cancer, including cathepsin D, glyceraldehyde-3-phosphate dehydrogenase, intercellular adhesion molecule 1, mesothelin, and tissue factor." (PMID 25987888, 2015). "MSLN is a tumour associated antigen in pancreatic cancer and is a target for immunotherapy." (PMID 24520352, 2014).
pancreatic cancer (continued). "Mesothelin is a tumor-associated antigen (TAA) in patients with pancreatic cancer that could be used to gauge cellular immune responses directed against transformed cells since up to 100 percent of pancreatic ductal adenocarcinoma cells have been shown to strongly express mesothelin." (PMID 29854291, 2018). "MSLNpep-kla also induced cytotoxicity in patient-derived pancreatic cancer organoids proportionate to MSLN expression." (PMID 42125244, 2026). "Analysis of a public single-cell RNA-sequencing dataset of human pancreatic cancer tissues revealed that MSLN was predominantly expressed in malignant ductal cells while showing negligible expression in normal ductal cells and stromal cells." (PMID 42125244, 2026). "Together, these findings reinforce the notion that MSLN is critical for maintaining proliferative capacity and genomic stability in pancreatic cancer cells." (PMID 40563707, 2025). "In our previous study, we examined the effect of MSLN on pancreatic cancer cell proliferation, cell cycle progression, the expression of cell cycle regulatory proteins, and signal transduction pathways in different PDAC cell lines." (PMID 40563707, 2025). "MSLN expression in pancreatic cancer was significantly higher compared to adjacent tissues (p < 0.0001)." (PMID 39887656, 2025). "Anti‐MSLN antibody (αMSLN) treatment of pancreatic cancer in vivo can significantly increase T cell infiltration." (PMID 39887656, 2025). "Here, three datasets and multi‐immunofluorescence staining of tissue microarrays in pancreatic cancer indicate that mesothelin (MSLN) expression negatively correlates with cytotoxic T cells in tumor." (PMID 39887656, 2025). "MSLN is a glycoprotein neo-expressed and released from the cell membrane in pancreatic cancer to reach the bloodstream." (PMID 40164585, 2025). "MSLN is highly expressed in most pancreatic cancer cells and is considered to be an attractive therapeutic target." (PMID 39887656, 2025). "Antigenic targets evaluated for CAR-T for pancreatic cancer in preclinical or clinical models notably include prostate stem cell antigen, mesothelin (MSLN), CEACAM7, CEA, HER2, Mucin-1, FAP, and others." (PMID 40723238, 2025). "Targeting mesothelin (MSLN) improved neoantigen vaccine efficacy in pancreatic cancer by reducing apCAFs, which disrupted the conversion of naive CD4+ T cells into Tregs and enhanced the infiltration of IFN‐γ+CD4+ and GZMK+CD8+ T cells." (PMID 39887656, 2025). "Although the prognostic role of MSLN in patients with ovarian and gastric cancers remains controversial, data derived from pancreatic cancer studies consistently indicate that high MSLN expression portends an unfavorable prognosis for patients." (PMID 41400642, 2025). "In vitro, HSV-MSLN effectively induced MSLN expression on murine pancreatic cancer cells, with subsequent cell lysis." (PMID 40366419, 2025). "These radio-labeled Amatuximab complexes were tested in a pancreatic cancer xenograft model, showing MSLN-specific accumulation and a significant reduction in tumor mass, accompanied by overall toxicity." (PMID 41335396, 2025). "In the study by Sato and colleagues (2003), MSLN is one of the genes overexpressed in pancreatic cancer due to selective DNA hypomethylation." (PMID 41335396, 2025). "They studied PD-1 KO anti-mesothelin CAR T cells in nine patients (six pancreatic, two ovarian, and one colorectal carcinomas), as well as TRAC + PD-1 KO anti-mesothelin CARs in 15 (six pancreatic cancer, three biliary carcinoma, and six other)." (PMID 41354926, 2025). "Utilizing tumor transcriptomic data from 183 pancreatic cancer patients in The Cancer Genome Atlas (TCGA), we analyzed the correlation between MSLN expression and the gene signature of CD3+CD8+ T cell population." (PMID 39887656, 2025).